AFP (alpha fetoprotein)
Diseases named in the same sentence as AFP in open-access papers (continued):
Sharing a sentence is not in itself a finding about the gene and the disease.
colorectal cancer (continued). "To date, only 11 cases of AFP-producing colorectal cancer have been reported." (PMID 25962419, 2015). "However, AFP-producing colorectal cancer is extremely rare because the colorectum originates from the hindgut endoderm." (PMID 25962419, 2015). "Only 11 cases of AFP-producing colorectal cancer have been reported in English literature to date." (PMID 25962419, 2015). "Interestingly, there are similarities with AFP-producing colorectal cancer and AFP-GC that it rapidly progresses and frequently metastasizes into the liver and show poor prognosis." (PMID 25962419, 2015). "Hence, to monitor patients with an oncological history, particularly of colorectal cancer, and an unexplained mass in the liver, it is necessary to screen the α-fetoprotein (AFP) level." (PMID 25364458, 2014). "Consequently, AFP production is an abnormal physiological response in colorectal cancer, which may serve as an important clinical indicator related to the course of the disease and may be useful in diagnostic and therapeutic approaches." (PMID 40430002, 2025). "Carcinoembryonic antigen (CEA), carbohydrate antigen 19-9 (CA19-9), carbohydrate antigen 125 (CA125), and alpha-fetoprotein (AFP) are widely used tumor markers for colorectal cancer (CRC), but their clinical significance is unknown when the levels of these tumor markers were within the normal range." (PMID 38129505, 2023). "However, it is extremely rare that AFP is produced in colorectal cancer." (PMID 30191347, 2018). "However, the histological characterization of AFP-producing colorectal cancer differs from AFP-GC." (PMID 25962419, 2015). "Traditional gastrointestinal tumor markers include AFP, CEA, CA199, CA125, CA153, and CA724, which have low sensitivity and specificity for diagnosing colorectal cancer but are commonly used for disease screening and monitoring recurrence." (PMID 41040534, 2025). "Previous studies reported colorectal cancer diagnosis using serum CEA, AFP, and CA19-9, achieving sensitivities of 80.43%, 73.91%, and 69.57%, and specificities of 75.00%, 69.44%, and 61.11%, respectively." (PMID 36970057, 2022). "The HSP90α was measured by using the ELISA kit in all objects and the immune cells and common biomarkers as CEA, AFP, CA125, CA153 and CA199 were measured in all colorectal cancer patients." (PMID 34307453, 2021). "There was no statistical correlation between common tumor markers CEA, AFP, CA125, CA153, CA199, TK1 and immune cells in patients with colorectal cancer (all p > 0.05)." (PMID 34307453, 2021). "DUPAN-2 is a well-known tumor marker for pancreatic, bile duct, and colorectal cancers; in our case, serum DUPAN-2 levels, as well as AFP, were increased before orchiectomy." (PMID 27150447, 2016). "Furthermore, it was shown that the blood concentration of tumor markers, such as alpha-fetoprotein (AFP) or carcinoembryonic antigen (CEA), increased exponentially in patients with gastric or colorectal cancers." (PMID 28795270, 2018). "Although our case was pathologic stage I which was not normally needed for adjuvant chemotherapy in AFP-negative colorectal cancer, he was deemed to have a high probability of recurrence, and hence, adjuvant chemotherapy was performed." (PMID 30191347, 2018). "As effective therapies against AFP-producing colorectal cancer have not been established, regimen is performed according to various guidelines and personal experiences." (PMID 30191347, 2018). "The expression of AFP was significantly up‐regulated by CD39 over‐expression, whereas down‐regulated by CD39 knockdown, indicating that CD39 could enhance the cell invasion of colorectal cancer cells." (PMID 40052646, 2025). "Murakami and colleagues identified five CAED patients (0.3%) from 1,666 patients with colorectal carcinomas whose clinical pathological features were analyzed followed by IHC staining with enteroblastic lineage markers: glypican-3 (GPC-3), spalt-like transcription factor 4 (SALL4), and AFP." (PMID 37781207, 2023).
colorectal cancer (continued). "Tumor markers (TMs), such as alpha fetoprotein (AFP), carcinoembryonic antigen (CEA), cancer antigen 19-9 (CA19-9) and cancer antigen 72-4 (CA72-4), have been widely used for the diagnosis of different types of cancers, including liver, colorectal cancer and pancreatic cancers." (PMID 27385101, 2016). "In addition, immunohistochemistry staining demonstrated that AFP, CEA, and E-cadherin showed strong positive expressions in both tumor tissues, indicating that the biological characteristics of the primary tumor were well preserved in the colorectal cancer PDX model." (PMID 36742145, 2023). "Kaplan–Meier survival analyses of seven serum tumor markers in colorectal cancer patients undergoing radical surgery with normal preoperative CEA showed that, for NSE and AFP, negative and positive groups displayed no notable disparities (p > 0.050)." (PMID 38067346, 2023). "In addition, serum IL-41 expression was significantly higher in AFP-negative HCC patients than in AFP-positive HCC patients, colorectal cancer (CRC) patients with liver metastases, and healthy control." (PMID 38835390, 2024).
hepatoid adenocarcinoma (53 papers, 2005 to 2026). An adenocarcinoma with morphologic characteristics similar to hepatocellular carcinoma, arising from an anatomic site other than the liver. "Although most cases of hepatoid adenocarcinoma are associated with AFP levels, an elevated AFP is only suggestive." (PMID 38071759, 2023). "While AFP exhibits limited sensitivity in GC, aberrant elevation may indicate aggressive biological behavior, such as hepatoid adenocarcinoma, which is typically associated with poor prognosis." (PMID 40977738, 2025). "In a previous study of hepatoid adenocarcinomas, AFP was positive in 80% cases, SALL4 was positive in 47%, HepPar‐1 was positive in 69%, and GPC3 was positive in 56%." (PMID 41190289, 2026). "Hepatoid adenocarcinoma (HAC) is a specific extrahepatic adenocarcinoma with hepatocellular differentiation, often associated with elevated serum alpha-fetoprotein (AFP)." (PMID 40740864, 2025). "AFP-producing adenocarcinomas consist of two histological subtypes, hepatoid adenocarcinoma and adenocarcinoma, with fetal gut-like features, and both of these subtypes, in some cases, can co-exist." (PMID 38817451, 2024). "Hepatoid adenocarcinoma (HAC) is a poorly differentiated extrahepatic tumor that can produce alpha-fetoprotein (AFP)." (PMID 38577906, 2024). "On the other hand, for patients with hepatoid adenocarcinoma accompanied by an elevated AFP, the AFP levels should be periodically reviewed to assist in determining tumor recurrence and metastasis." (PMID 37950062, 2023). "While serum AFP levels are vital in hepatoid adenocarcinoma diagnosis, a conclusive diagnosis hinges upon a comprehensive evaluation that combines histological morphology and immunohistochemical markers." (PMID 37950062, 2023). "Previous studies have shown that AFP-positive hepatoid adenocarcinoma is more prone to liver metastasis, and higher AFP levels are associated with a higher rate of liver metastasis." (PMID 37950062, 2023). "Several studies indicated that 70–80% of hepatoid adenocarcinoma (HAC) patients exhibit elevated serum AFP levels." (PMID 37950062, 2023). "Combining the abnormal elevation of serum AFP and microscopic pathological morphology, this case is diagnosed as hepatoid adenocarcinoma of the duodenum with liver metastasis." (PMID 36003790, 2022). "Hepatoid adenocarcinoma is a poorly differentiated alpha-fetoprotein-producing (AFP) tumor frequently located in the stomach, ovary, and pancreas." (PMID 34221269, 2021). "Both gastric adenocarcinoma with primitive enterocyte phenotype (GAPEP) (including hepatoid adenocarcinoma) and alpha-fetoprotein (AFP)-producing gastric adenocarcinoma have poor prognoses." (PMID 34706681, 2021). "Here, we describe a very rare case of a young female on her 21st week of pregnancy who was diagnosed with stage IV hepatoid adenocarcinoma of the stomach with elevated α fetoprotein (AFP) level." (PMID 34527251, 2021). "This is an unusual case of uterine carcinosarcoma with an alpha-fetoprotein-producing hepatoid adenocarcinoma component." (PMID 29992073, 2018). "This was important for diagnosis of hepatoid adenocarcinoma, including immunoreactive AFP in the cytoplasm of cells in the trabecular or solid nests." (PMID 26976278, 2016). "Immunohistochemical staining of a transbronchial lung biopsy revealed that the tumor cells were α-fetoprotein (AFP)(positive) and hepatocytes(positive) and a diagnosis of hepatoid carcinoma of the left lung was established." (PMID 24959228, 2014). "Alpha-fetoprotein-producing carcinoma (AFPC)/hepatoid adenocarcinoma (HAC) and neuroendocrine carcinoma (NEC) are uncommon in the stomach." (PMID 22482081, 2012). "Immunohistochemically, AFP is found in both the hepatoid component and the papillary component of hepatoid carcinomas." (PMID 21554678, 2011). "Almost all hepatoid adenocarcinomas, both primary and metastatic adenocarcinomas, are reported as AFP positive." (PMID 24281095, 2010).
hepatoid adenocarcinoma (continued). "The specificity of AFP for HCC is being challenged by reports of AFP-producing extrahepatic hepatoid/non-hepatoid carcinomas." (PMID 15941489, 2005). "These hepatoid adenocarcinoma cases displayed hepatoid differentiation, such as the formation of cords of polygonal cells, bile canaliculi formation, or evidence of bile production, and positive AFP staining." (PMID 40406259, 2025). "Hepatoid adenocarcinoma is the main pathological feature of alpha‐fetoprotein (AFP) CRC." (PMID 35285179, 2022). "In our study, 61.70% of patients with HAS had significantly elevated serum AFP levels, which may be a result of the dedifferentiation of cancer cells into hepatoid adenocarcinoma progenitor cells." (PMID 34956891, 2021). "Notably, compared with the serum AFP < 20 ng/ml group, 10 (13.5%) patients were diagnosed with hepatoid adenocarcinoma in the AFP ≥ 20 ng/ml group." (PMID 29434637, 2017). "Therefore, the diagnosis of hepatoid adenocarcinoma should be strictly based on combination of hepatoid features and AFP secretion." (PMID 26976278, 2016). "Rare cases of AFP-producing pNETs have been described in the English literature, but these tumors usually coexisted with other malignant components such as adenocarcinoma or hepatoid carcinoma." (PMID 25886790, 2015). "On immunohistochemistry, hepatoid adenocarcinomas may express alpha-fetoprotein (AFP), albumin, transferrin, PIVKA, and alpha-1-antitrypsin." (PMID 26421012, 2015). "Many patients with hepatoid carcinoma have an elevated serum AFP level at presentation." (PMID 22559879, 2012). "Hepatoid adenocarcinoma shows several pathological overlaps with YST, as both glandular and hepatocellular differentiation with AFP production." (PMID 33956241, 2021). "One possibility is that hepatoid adenocarcinoma produces AAT (alpha-1 antitrypsin) and/or ACT (alpha-1 antichymotripsin) as well as AFP." (PMID 19674468, 2009). "The prognosis of patients with hepatoid adenocarcinoma, regardless of AFP elevation, is generally worse than that of ordinary adenocarcinoma." (PMID 37950062, 2023). "Nagai et al3 believed that gastric hepatoid adenocarcinoma can be diagnosed by the histomorphology of hepatoid adenocarcinoma, because it does not depend on the production of AFP." (PMID 38071759, 2023). "Hepatoid adenocarcinoma (HAC) is a rare histopathological subtype of adenocarcinoma characterized by prominent hepatocyte-directed differentiation and the characteristic secretion of alpha-fetoprotein (AFP)." (PMID 37950062, 2023). "The 2020 WHO Classification of Female Geniatal Tumors does not mention AFP+ EC or hepatoid carcinoma." (PMID 34977100, 2021). "Alpha-fetoprotein (AFP)-producing pancreatic neuroendocrine tumors (pNETs) are rare, and the few reported cases usually coexisted with other malignant components such as adenocarcinoma or hepatoid carcinoma." (PMID 25886790, 2015). "While AFP remains the most important marker of this lesion, not all hepatoid adenocarcinomas are positive for AFP." (PMID 26421012, 2015). "• Hepatoid carcinoma; AFP-producing carcinoma: Primary hepatic tumors are not the only source of AFP." (PMID 15941489, 2005). "Non-clear glandular AFP+ EC and hepatoid carcinoma might resemble low-grade and high-grade endometrioid carcinoma, respectively." (PMID 34977100, 2021). "To date, no cases of endometrial fetal gut-like or hepatoid carcinoma without elevated serum AFP levels have been reported, but this may be due to publication bias." (PMID 34977100, 2021). "Subsequent researchers found that some patients with hepatoid adenocarcinoma did not express AFP." (PMID 31915699, 2019).
Portal vein thrombosis (50 papers, 2011 to 2025). Thrombosis of the portal vein and/or its tributaries, which include the splenic vein and the superior and inferior mesenteric veins. "Infiltrative HCC is commonly associated with portal vein thrombosis, high levels of alpha-fetoprotein (AFP), and very poor prognosis." (PMID 35200560, 2022). "Glypican-3 (GPC3) showed a significant positive correlation with alpha-fetoprotein expression, while elevated alpha-fetoprotein level has reported to be associated with portal vein thrombosis." (PMID 33996895, 2021). "Brian Carr and Guerra (2016) found a considerable difference in survival between patients with elevated and low serum AFP levels associated with portal vein thrombosis." (PMID 30112355, 2018). "In HCC patients, elevated bilirubin levels were associated with higher AFP levels, increased portal vein thrombosis and multifocality and lower survival." (PMID 28674386, 2017). "Multivariate analysis of factors associated with tumor progression indicated that ascites, prothrombin time>12 seconds, AST>ULN, portal vein thrombosis, AFP>400 ng/ml, and positive TACO were associated with a shorter disease-free survival (DFS)." (PMID 27779207, 2016). "We noted that PNI correlated significantly with raised AFP, liver functional reserve and the presence of portal vein thrombosis suggesting that a high risk PNI correlates with a more aggressive disease phenotype." (PMID 22433965, 2012). "The Cox regression analysis showed that in univariate models, higher mortality was associated with age, AFP levels, ALD etiology, Child–Pugh and BCLC stages, TNM stage, malignant portal vein thrombosis (PVT), and comorbidities." (PMID 40427157, 2025). "The incidences of portal vein thrombosis, tumor multifocality, and high AFP levels were also increased in patients with elevated bilirubin levels, regardless of the primary tumor size." (PMID 38429725, 2024). "We evaluated the role of baseline laboratory values, such as albumin, bilirubin, Alpha fetoprotein (AFP), Portal vein thrombosis (PVT), etc. as significant factors for predicting OS." (PMID 38981950, 2024). "The BCLC includes five prognostic factors: portal vein thrombosis, multifocal tumor, diffuse or massive disease, high alpha-fetoprotein (AFP) levels, and performance status." (PMID 35744805, 2022). "Portal vein thrombosis (HR 4.3, 95% C.I. 1.5–12.8) and AFP > 400 ng/mL (HR 3.3, 95% C.I. 1.1–9.3) were poor prognostic factors and nivolumab used remained a protective factor (HR 0.2, 95% C.I. 0.1–0.7)." (PMID 35477812, 2022). "CLIP basically uses the same set of variables as the Okuda staging but added AFP and the presence of portal vein thrombosis to the assessed patient characteristics." (PMID 33294952, 2021). "The Cancer of the Liver Italian Program (CLIP) includes the number of nodes, alpha-fetoprotein (AFP) level (>400ng/dL), portal vein thrombosis and Child-Turcotte-Pugh (CTP), classification." (PMID 29617435, 2018). "Based on the small variable set included into calculating the score (tumor volume compared to liver volume, Child-Pugh category, AFP, and the presence of portal vein thrombosis), CLIP is feasible to be used in surgical candidates and does display decent prognostic ability in our current study." (PMID 33294952, 2021). "As far as liver tests are concerned, we confirmed the independent negative prognostic meaning of bilirubin levels as an index of baseline liver function which can be further hampered by features of tumor extension/aggressiveness, such as portal vein thrombosis, multifocality and higher AFP." (PMID 34072309, 2021). "A large tumor size, bilobar involvement, massive or diffuse types, and portal vein thrombosis might contribute to the high levels of AFP." (PMID 31355135, 2019).
Portal vein thrombosis (continued). "Multifocal or diffuse HCC, presence of extra-hepatic metastasis, portal vein thrombosis, hypoalbuminemia, hyperbilirubinemia, high AFP, alkaline phosphatase and creatinine were consistently significant clinical factors associated with shorter OS in all multivariate analyses." (PMID 28052758, 2017). "However, the expression of HSF1 was not correlated to HCC patient age, gender, HBV infection status, AFP expression levels, Ceacam1 expression levels and portal vein thrombosis." (PMID 25199534, 2014). "The indicators that reflect the aggressiveness of liver cancer were the presence of portal vein thrombosis (PVT), tumor size, tumor multifocality, and AFP levels." (PMID 35411218, 2022). "Subgroup analysis suggests that patients who are male, HBsAg-positive, have AFP ≤400 ng/mL, Child-Pugh A, multiple tumors, tumor size ≤5 cm, absence of portal vein thrombosis, and those receiving TACE benefit more significantly from the combination therapy." (PMID 41019079, 2025). "A retrospective study found that HCC patients with high AFP tended to have more aggressive presentations of HCC, including greater tumor burden, massive or diffuse types, and portal vein thrombosis, which made AFP level a negative prognostic indicator." (PMID 36981582, 2023). "During 6 months of follow-up of the MSCs-treated patients (with ultrasonography, Doppler, and s-AFP), no focal lesions or portal vein thrombosis was detected." (PMID 24886681, 2014). "AFP level and portal vein thrombosis did not appear statistically significant for extrahepatic metastasis in a multivariate analysis." (PMID 21985636, 2011). "Another random forest Model 2 based on the selected 2 clinical features (ALT and AFP levels) and 1 general imaging feature (presence or absence of portal vein thrombosis) resulted in an AUC of 0.867 with a 95% confidence interval (CI) of 0.765–0.968 for predicting treatment response after TACE." (PMID 36869284, 2023). "Prior studies have proven the value of several features in predicting survival in HCC, including AFP level, ALT level, and presence or absence of portal vein thrombosis, similarly those features showed high importance in our random survival forest models." (PMID 36869284, 2023).